IL6 (interleukin 6)
Diseases named in the same sentence as IL6 in open-access papers (continued):
Sharing a sentence is not in itself a finding about the gene and the disease.
Sepsis (continued). "Importantly, we found that DMF also inhibited the LPS-induced cytokine production in LPS-stimulated RAW264.7 cells, including IL-6, G-CMF, TNF-α, and MCP-1, suggesting that DMF may have the potential to treat various inflammation-related diseases including sepsis." (PMID 37840694, 2023). "Therefore, increased levels of IL-6 do not necessarily reflect a pathological role in sepsis." (PMID 37762478, 2023). "However, sulodexide treatment did not reduce IL-6 levels during sepsis." (PMID 37614234, 2023). "Thus, in the present study, we utilized the cecal ligation and perforation (CLP) murine model, a classic model of SI‐AKI, to assess whether the progression of sepsis‐induced renal injury is epigenetically regulated by PRMT1 through the TGF‐β1/Smad3 and IL‐6/STAT3 pathways." (PMID 37525933, 2023). "Hence, when managing sepsis in elderly patients, it might be more critical to monitor the sequential changes in serum IL-6 concentrations rather than measuring them once above a designated, detectable threshold." (PMID 37214473, 2023). "Our study showed that the concentration of albumin in blood tended to be lower in patients with KD combined with severe sepsis than in patients with KD combined with non-severe sepsis (P=0.082) and may reflect the significantly elevated levels of cytokines, such as IL-6." (PMID 37234775, 2023). "The results showed that IL-1β, IL-6, and TNF-α contents of model group increased markedly vs. control and interference groups, suggesting that IL-17RA-1 might promote the secretion of proinflammatory factors by THP-1-M1 cells, contributing to the development of sepsis." (PMID 36274974, 2022). "In addition, PLX-R18 administration attenuated biomarkers of bone marrow aplasia, sepsis, and systemic inflammation and attenuated radiation-induced inflammatory cytokines/chemokines and growth factors, including G-CSF, MIP-1a, MIP-1b, IL-2, IL-6 and MCP-1, and modulate AKT protein expression." (PMID 36292639, 2022). "It was noted that IL-6 showed the strongest correlation with the severity of illness, followed by the NLR and PCT, which indicated that these biomarkers might be effective indicators in stratifying disease severity in order to give the prediction the prognosis of the patients with sepsis." (PMID 33796105, 2021). "However, antibody drugs targeting cytokines (e.g., tumor necrosis factor [TNF] and interleukin 6 [IL6]), inflammatory pathways (e.g., toll like receptor 4 [TLR4]), or endotoxin, as well as empiric antibiotic therapies have little or disappointing benefit for patients with sepsis." (PMID 33776776, 2021). "Therefore, the effect of CaD to decrease CD14 and TLR4 expression could offer one mechanism to explain why CaD inhibits NF-κB and suppresses the release of downstream NF-κB activation products—TNFα, IL-1β, IL-6, and MCP-1 in animal models of sepsis and diabetic nephropathy and retinopathy." (PMID 34829669, 2021). "Similarly, in a hemorrhage induced sepsis mouse model, intratracheal delivery of siRNA to locally silence chemoattractant cytokines KC and MIP-2 significantly suppressed neutrophil influx into the lungs and decreased tissue or plasma level of IL-6, MIP-2 and MPO, activity." (PMID 35111077, 2021). "However, the role of IL-6 signaling in sepsis-induced muscle atrophy is not well understood." (PMID 34572540, 2021). "Thus alternative therapeutic options such as anti-inflammatory drugs could be beneficial as neonatal sepsis is characterized by elevated levels of inflammatory cytokines such as tumor necrosis factor alpha (TNF-α) and interleukin 6 (IL-6) which amplifies the severity of sepsis." (PMID 32076015, 2020). "Moreover, previous studies of sepsis and ALI have demonstrated that HIF-1α expression may induce acute lung epithelial damage and the production of numerous proinflammatory cytokines such as IL-6, MIP-2 and TNF-α via the nuclear factor-κB (NF-κB) pathway." (PMID 32353952, 2020).
Sepsis (continued). "Although the experimental model of infectious disease (e.g., malaria and sepsis) and autoimmune disease (e.g., RA and SLE) indicates that artemisinin-family drugs could target the inflammatory networks to decrease the levels of cytokines (e.g., IL-6 and TNF-α) and chemokines (e.g., IL-8, CXCL10)." (PMID 32754163, 2020). "In this setting, we demonstrated that IL-6 levels (with higher 39.32 pg/ml) have a high negative predictive value of prognosis in nonseptic critically ill children, which was consistent with the results of previous studies in neonatal/pediatric critically ill patients with sepsis." (PMID 32695814, 2020). "However, blood samples from sepsis patients need to be tested for IRAK3, TNF-α and IL-6 protein levels at more time intervals after endotoxin challenge to clarify whether the patterns of temporal expression of these molecules reflect in vitro human cell culture models." (PMID 33382782, 2020). "However, in foals evidence suggests that IL-6 protein is lower in the blood of septic vs. healthy foals and that the IL6:IL10 ratio, which was higher in the healthy age matched foals compared to septic foals, may be a useful prognostic indicator for neonatal septicemia." (PMID 30931316, 2019). "There is growing evidence that pro-inflammatory cytokines such as interleukin-1 (IL-1), IL-6, and tumor necrosis factor-alpha (TNF-α) play a central role in the systemic complications of acute pancreatitis and may be involved in diaphragmatic dysfunction during sepsis." (PMID 30466472, 2018). "Since the lipopolysaccharide (LPS) from the cell wall of γ-negative bacteria like E. coli causes sepsis by inducing pro-inflammatory mediators including TNF-α and IL-6, this study detected whether MS19 could reduce the production of these inflammatory cytokines." (PMID 28492513, 2017). "However, other studies do not support the use of IL-6 as a valid sepsis biomarker." (PMID 28484510, 2017). "However, we found the value of IL-6 in diagnosing sepsis did not change in the subgroup population, indicating IL-6 may not be a valuable biomarker for our cohort of patients." (PMID 27287669, 2016). "In light of the notion that IL-6 and TNF-α promote wound healing and tissue repair, increased production of these cytokines may also limit pathogens from penetrating the epithelial lining of the intestine and invading into the peritoneal cavity to induce sepsis, an extreme case of IBD." (PMID 26439699, 2015). "Furthermore, muscle biopsies from healthy donors after IL-6 infusion (GSE10685) or patients with sepsis induced multiple organ failure (GSE13205) did not reveal any increase of the immunoproteasome expression, indicating that expression of PSMB8/-9 in muscle is specific for IIM." (PMID 25098831, 2014). "Furthermore, plasma levels of IL-1β, IL-6, MIP-2, and MIP-1α were obviously down-regulated in C5aR knockout mice when compared with wild type littermates, suggesting that the harmful effects of C5aR during sepsis might result from C5a-mediated cytokine storm." (PMID 23233853, 2012). "In neonatal sepsis, a single CRP value was found to be a poor predictor of sepsis, whereas serial CRP measurements were good predictors of late-onset sepsis (LOS) in very-low-birth-weight neonates, whether performed as single tests or in combination with tests of the interleukin-6 (IL-6) level." (PMID 22943554, 2012). "In contrast to HMGB1, IL-6 and KC may not critically important in the pathogenesis of sepsis, because neither anti-IL-6 nor anti-KC antibodies confer long-lasting protection against lethal sepsis." (PMID 17987129, 2007). "In patients presenting with infection without sepsis, MVHS demonstrated strong predictive discrimination for progression (AUC 0.79, p < 0.0001), outperforming procalcitonin and interleukin-6." (PMID 41998704, 2026).
Sepsis (continued). "We found that cord blood levels of IL-6 and IL-8 were significantly higher in the LOS group compared to preterm infants without sepsis, while neutrophil and monocyte counts in peripheral blood were lower in the LOS group." (PMID 40640885, 2025). "Correspondingly, the serum CRP levels of the six neonates did not peak within 12 h, indicating that serum IL-6 levels rapidly and significantly changed and were superior to CRP levels in monitoring the severity of sepsis." (PMID 40150583, 2025). "Given that IL-6 is not routinely measured in ICU settings, recent studies have increasingly adopted the mNUTRIC score to predict outcomes in patients with sepsis." (PMID 40823032, 2025). "Median values of IL-6, IL-18, and GDF15 were significantly higher in the sepsis and septic shock groups, compared to the non-sepsis group." (PMID 40681771, 2025). "Our results show significantly greater IL-6 values in cases of NEC compared with LOS, especially when blood cultures are negative (clinical sepsis without symptoms suggestive for NEC)." (PMID 39958363, 2025). "However, critically ill patients with and without septicemia could not be discriminated between in this way, and a lack of increase in IL-6 upon the preincubation of heparin blood was not correlated with diminished leukocyte counts and/or a lowered lymphocyte fraction." (PMID 40428180, 2025). "Baseline serum levels of ACSL4, GPX4, PTGS2, CL-11, IL-6, IL-8, PCT, and hs-CRP significantly differed among sepsis, non-septic, and healthy individuals (all p-value < 0.01)." (PMID 40264754, 2025). "In patients with sepsis/septic shock, LPC species showed negative correlations with procalcitonin and interleukin-6, and positive correlations with gamma-glutamyltransferase and cholesteryl ester levels." (PMID 41007672, 2025). "nDNA had areas under the receiver operating characteristic (ROC) curves of 0.78 for sepsis and 0.76 for negative outcome, which were higher than those of the other DAMPs and additional biomarkers (CRP, IL-6, IL-8, and IL-10)." (PMID 39379599, 2024). "In contrast to healthy volunteers, the coagulation response in sepsis patients is altered (e.g. thrombocytopenia or prolonged global coagulation times) and therefore the use of dual anticoagulatory strategies may ultimately not be required for haemofiltration with the IL-6-Sieve in sepsis patients." (PMID 38890397, 2024). "Accordingly, aging induction by D-gal worsened sepsis severity only in renal and liver injury, but not mortality, encephalopathy (SHIRPA score), and serum cytokines (IL-6 and TNF-α)." (PMID 39423218, 2024). "Numerous biomarkers, such as interleukin 6 (IL 6), interleukin 2 (IL 2), CRP, and PCT, have been extensively studied in an effort to distinguish infections from non-infectious causes of fever in sepsis patients, which could potentially aid in optimizing the use of antibiotics." (PMID 38681106, 2024). "In our SIRS/sepsis cohort plasma, apoA-IV was not correlated with leukocytes, CRP, procalcitonin or IL-6." (PMID 39311203, 2024). "Throughout all explored tissues, sepsis increased pro-inflammatory cytokines like TNFα, MCP-1, IL-10 and IL-6 compared to sham animals, regardless of HVEM:LIGHT blockade." (PMID 38774873, 2024). "All of them were significantly higher in patients with sepsis than in those without sepsis at several specific time points but only SAA, CRP, and PCT were found to be independently predictive of sepsis except IL-6 as shown in this study." (PMID 38182736, 2024). "The CD86%, neutrophil count, CRP/ALB, NLR, IL-6, IL-10, sIL-2R, CRP, and PCT levels were significantly higher, and the HLA-DR%, lymphocytes, PLT, and ALB levels were significantly lower in the sepsis group than in the non-sepsis group (all P<0.05)." (PMID 38603712, 2024). "Of note, IL-1b, IL-6, IL-10, TNF-a, and suPAR did not significantly change during the first week of sepsis (p > 0.05)." (PMID 39272772, 2024).
Sepsis (continued). "Here, LGG effectively attenuated sepsis as evaluated by all selected parameters in non-aging PBS-administered mice, while LGG neither reduced serum IL-6 nor improved organ injury in aged mice." (PMID 39423218, 2024). "IL-6 at a cut-off of 130 pg/mL demonstrated 100% sensitivity and 52% PPV when discriminating between patients without sepsis and those with sepsis (clinical or culture proven)." (PMID 38671704, 2024). "Pediatric burn patients with sepsis exhibit elevated serum levels of TNF-α and IL-6 as compared to their non-septic counterparts." (PMID 39716257, 2024). "In mice with SHP2 specifically ablated in macrophages, sCD4 no long improved the survival rates of LPS sepsis, nor inhibited TNF/IL-6 response." (PMID 37332010, 2023). "The administration of BAM15 particles or BAM15 alone in LPS-induced sepsis mice attenuated inflammatory cytokines (TNF-α and IL-6 but not IL-10) in kidneys." (PMID 38140036, 2023). "In sepsis mice, the production of liver TNF-α and IL-6 was also decreased by treatment with BAM15 particles but not BAM15, while the liver IL-10 level was not affected by all treatments." (PMID 38140036, 2023). "While SUL-138 partly limited systemic inflammation demonstrated by lowered plasma IL-6 and TNF-α and dampened a decrease in body temperature during sepsis, it did not mitigate the effects of CLP on white blood cell count." (PMID 37047303, 2023). "Specifically, the combination of IL6 and CRP has been suggested for identification of clinical sepsis in cases of negative bacterial culture." (PMID 37496672, 2023). "To address the expression of inflammatory factors in sepsis‐induced ALI, we tested the levels of CRP, PCT, and IL‐6 in patients with sepsis without ALI and patients with ALI." (PMID 37248197, 2023). "Similarly, the levels of TNF-α, IL-6, TGF-ß1, and NF-κB significantly increased in the model group and decreased in the Tα1, VitC, and Tα1 + VitC groups, indicating that combined Tα1 and VitC therapy may help regulate the immunological state of patients with sepsis, thereby improving prognosis." (PMID 36816800, 2023). "A study of 233 patients in 200917 reported that plasma HBP levels of ≥ 15 ng/mL was a better indicator of severe sepsis (with or without septic shock) than PCT, IL-6, CRP, WBC and lactate." (PMID 35750778, 2022). "A retrospective study evaluated a broad panel of cytokines and found IL-1β, IL-6, IL-8, MCP-1, IL-10, and plasminogen activator inhibitor 1 (PAI-1) levels were increased in the acute phase of sepsis in both critically and non-critically ill patients." (PMID 34991675, 2022). "Higher levels of IL-6 (202.92 to 1.81 pg/ml) and IFN-γ (1.74 to 0.28 pg/ml) were found in the sepsis compared to the non-sepsis patients' group, although differences were not statistically significant." (PMID 35582414, 2022). "GO analysis revealed that IL-6 can be measured to distinguish NEC from nonsepticemia-related diseases, although it is difficult to distinguish NEC from septicemia." (PMID 36371157, 2022). "Serum levels of IL-6 and TNF-α are highly elevated in newborns with sepsis compared to healthy newborns, and lower in the survivors of elderly patients with sepsis than non-survivors, indicating their relation to inflammatory syndrome of sepsis." (PMID 35167625, 2022). "On the fifth day of modeling, the levels of IL-1β, IL-6, and TNF-α in the mouse serum were not significantly different between the sepsis and sepsis-AW group but were significantly higher than those in the normal control group." (PMID 36016684, 2022). "Circulating IL-6 rather than procalcitonin, WBC, and body temperature had the clinical utility to predict the early stage of sepsis in burned patients." (PMID 35884890, 2022). "Regardless of the pretreatment they received, sepsis equally increased the mRNA levels of TNF-α, IL-1, IL-6 (p < 0.001) and IL-10 (p < 0.01) in both groups of septic rats." (PMID 35795581, 2022).
Sepsis (continued). "Using CLP, a clinically relevant murine model of gram-negative polymicrobial sepsis, we observed that FeTPPS treatment markedly inhibited caspase-11-dependent release of IL-1α and IL-1β, but did not affect the secretion of TNF or IL-6." (PMID 33854044, 2021). "None of the dogs in this study suffered from sepsis; therefore, we can assume that the levels of TNF-α and IL-6 do not increase in pancreatitis without septic conditions." (PMID 33803665, 2021). "A significantly increased concentration of IL-6 as early as at the time of hospital admission was found in dogs with pancreatitis, non-infectious SIRS and sepsis, and trauma." (PMID 34222394, 2021). "There were also statistically significant differences in IL-6, sTREM-1, and PCT median concentrations between the group of feverish patients without diagnosed SIRS (N-SIRS) and patients with SIRS/sepsis." (PMID 32655314, 2020). "Its levels were evaluated, as usual, in blood samples obtained post mortem from cadavers divided in sepsis-related deaths group, local infections group, and non-sepsis ICU patients group, and compared to PCT, CRP, IL-6, and sTREM-1 levels." (PMID 33092081, 2020). "Simvastatin treatment was able to reduce the levels of TNF-α, IL-6, MIF, and IL-1β 24 hours after sepsis induction, indicating an important negative immunomodulary effect of simvastatin in this model." (PMID 33110395, 2020). "A significant decline in IL-6 levels at 6 h post ICU admission was observed in the ICU survivors with sepsis, but not in those without sepsis." (PMID 32635454, 2020). "The NGAL and IL-6 levels were significantly higher in patients with sepsis than in those without sepsis (NGAL: 454 (IQR, 240–690) vs. 155 (IQR, 74–331) ng/mL; IL-6: 32325 (IQR, 7029–51,380) vs. 642 (IQR, 93–1141) pg/mL)." (PMID 32635454, 2020). "Narciclasine treatment showed significant reduction of inflammatory cytokines (TNF-α, IL-6, IL-1β and IFN-γ) in liver homogenates compared to the sepsis group without treatment." (PMID 32076015, 2020). "Although different screening tools and biomarkers, such as white cell count, neutrophil count, interleukin 6 (IL-6), CRP, and PCT, have been used for sepsis diagnosis, none of them is proven to be specific." (PMID 33292630, 2020). "When nonsurvivors of the two groups were compared, the levels of serum IL-1β, IL-2R, IL-6, IL-8, and TNF-α were also lower in SARS-CoV-2 sepsis nonsurvivors." (PMID 33329592, 2020). "Treatment with narciclasine significantly reduced the levels of inflammatory cytokines TNF-α, IL-6, IL-1β and IFN-γ in lung homogenates when compared to the sepsis group without treatment." (PMID 32076015, 2020). "A retrospective cohort study of the cytokine response to pneumonia found that levels of IL-6, IL-10, and TNF-α were significantly higher among those who developed severe sepsis (survivors and non-survivors) compared with those who did not." (PMID 32144519, 2020). "Mean IL-6, sTREM-1, and PCT serum concentrations were statistically significantly higher in the group of patients with SIRS/sepsis compared to the group of feverish patients without diagnosed SIRS (N-SIRS)." (PMID 32655314, 2020). "The cytokines IL-6, IL-8, KC-like, and RANTES appear to be important for the pathogenesis of both sepsis and septic shock in cats, but these biomarkers are not discriminating for sepsis severity or outcome." (PMID 32548135, 2020). "In conclusion, our results suggest that IL-6 is better than PCT and CRP to predict the treatment success of non-surgical sepsis within the first 48–72 h." (PMID 30760225, 2019). "C-reactive protein (CRP), interleukin-6 (IL-6), procalcitonin (PCT) and other biomarkers are also used to detect sepsis, but none of these can adequately predict the outcome of sepsis." (PMID 31568522, 2019). "In patients with sepsis, non-survivors had significantly lower plasma iron, EPO and sTfR/log ferritin, but higher plasma hepcidin, ferritin and IL-6 than survivors on days 1, 3 and 7 of ICU admission." (PMID 31183575, 2019).